FHDC1 (FH2 domain containing 1)
Description:
Microtubule-associated formin which regulates both actin and microtubule dynamics. Induces microtubule acetylation and stabilization and actin stress fiber formation. Regulates Golgi ribbon formation. Required for normal cilia assembly. Early in cilia assembly, may assist in the maturation and positioning of the centrosome/basal body, and once cilia assembly has initiated, may also promote cilia elongation by inhibiting disassembly.
Synonyms: INF1; KIAA1727
Tractability: PROTAC: ubiquitination databases record sites on it.
Gene: Protein-coding gene on chromosome 4 (152,935,887 to 152,979,697, forward strand). Ensembl gene ENSG00000137460.
Subcellular location: Cell projection, cilium; Golgi apparatus
Subcellular location (Human Protein Atlas): Basal body; Centrosome; Primary cilium
Gene Ontology:
Molecular function: actin binding; microtubule binding
Biological process: cilium assembly; Golgi ribbon formation; stress fiber assembly; actin filament polymerization
Cellular component: cilium; microtubule; actin filament; cytoplasmic microtubule; Golgi apparatus
Genetic constraint (gnomAD): Loss-of-function variants: 21 observed, 45.07 expected, observed/expected ratio (o/e) 0.47, 90% interval 0.33 to 0.67. The upper end of that interval is the gene's LOEUF score, 0.67, which puts it in group 2 of 6, group 1 being the genes least tolerant of losing a copy. Missense variants: 1,390 observed, 1,395.3 expected, observed/expected ratio (o/e) 1, 90% interval 0.95 to 1.04. Synonymous variants: 589 observed, 561.91 expected, observed/expected ratio (o/e) 1.05, 90% interval 0.98 to 1.12.
Homologues: Orthologues: chimpanzee FHDC1 (99% identical), macaque FHDC1 (95% identical), dog FHDC1 (73% identical), rat Fhdc1 (73% identical), mouse Fhdc1 (73% identical), rabbit FHDC1 (72% identical), pig FHDC1 (72% identical), guinea pig FHDC1 (57% identical), tropical clawed frog fhdc1 (45% identical), zebrafish fhdc1 (38% identical), Caenorhabditis elegans exc-6 (17% identical), zebrafish fhdc5 (14% identical), and 3 more. Paralogues in human: INF2 (17% identical), DIAPH1 (13% identical), DIAPH3 (13% identical), DAAM1 (13% identical), DAAM2 (13% identical), FMNL2 (12% identical), FHOD3 (12% identical), DIAPH2 (12% identical), FMN2 (12% identical), FMNL3 (11% identical), FHOD1 (11% identical), FMNL1 (11% identical), and 6 more.
Diseases named in the same sentence as FHDC1 in open-access papers:
FHDC1 is named in the same sentence as 15 diseases in open-access papers, as found by Europe PMC text mining. Sharing a sentence is not in itself a finding about the gene and the disease. The quoted sentences say what the papers report.
lung adenocarcinoma (1 paper, 2022). A carcinoma that arises from the lung and is characterized by the presence of malignant glandular epithelial cells. "A study in lung adenocarcinoma reported that the high expression of FHDC1 was associated with significantly improved survival outcomes compared with that of low expression." (PMID 35909471, 2022).
ovarian carcinoma (1 paper, 2025). A malignant neoplasm originating from the surface ovarian epithelium. "For instance, LINC00665 enhances FHDC1 expression in ovarian cancer by binding to and inhibiting miR-181a-5p, thus accelerating cancer development and presenting a potential new therapeutic target for ovarian cancer." (PMID 40999508, 2025).
cancer (1 paper, 2022). A tumor composed of atypical neoplastic, often pleomorphic cells that invade other tissues. "The expression of FHDC1 is increased in various cancers including CRC and at its highest level in stage 1 cancer." (PMID 35909471, 2022).
FHDC1 also shares sentences with these, for which no sentence is quoted: infection (12 papers); tumor (3); COVID-19 (2); Azoospermia (1); basophilic leukemia (1); breast carcinoma (1); colorectal cancer (1); Cough (1); Klinefelter syndrome (1); SARS-CoV infection (1); tracheitis (1); viral infection (1).